ENSG00000288656 (novel transcript)
Gene: Long non-coding RNA gene on chromosome 16 (28,592,055 to 28,623,363, reverse strand). Ensembl gene ENSG00000288656.
Genetic constraint (gnomAD): Loss-of-function variants: 26 observed, 28.18 expected, observed/expected ratio (o/e) 0.92, 90% interval 0.68 to 1.28. Missense variants: 282 observed, 273.22 expected, observed/expected ratio (o/e) 1.03, 90% interval 0.94 to 1.14. Synonymous variants: 106 observed, 96.14 expected, observed/expected ratio (o/e) 1.1, 90% interval 0.94 to 1.3.